TOP1MT (DNA topoisomerase I mitochondrial)
Description:
Releases the supercoiling and torsional tension of DNA introduced during duplication of mitochondrial DNA by transiently cleaving and rejoining one strand of the DNA duplex. Introduces a single-strand break via transesterification at a target site in duplex DNA. The scissile phosphodiester is attacked by the catalytic tyrosine of the enzyme, resulting in the formation of a DNA-(3'-phosphotyrosyl)- enzyme intermediate and the expulsion of a 5'-OH DNA strand. The free DNA strand then rotates around the intact phosphodiester bond on the opposing strand, thus removing DNA supercoils. Finally, in the religation step, the DNA 5'-OH attacks the covalent intermediate to expel the active-site tyrosine and restore the DNA phosphodiester backbone (By similarity).
Tractability: Small molecule: an approved drug acts on it; it belongs to a druggable protein family. PROTAC: ubiquitination databases record sites on it.
Gene: Protein-coding gene on chromosome 8 (143,304,384 to 143,359,979, reverse strand). Ensembl gene ENSG00000184428.
Subcellular location: Mitochondrion
Subcellular location (Human Protein Atlas): Mitochondria
Gene Ontology:
Molecular function: DNA binding; DNA topoisomerase type I (single strand cut, ATP-independent) activity
Biological process: DNA replication; DNA topological change
Cellular component: mitochondrial nucleoid; mitochondrion; chromosome
Genetic constraint (gnomAD): Loss-of-function variants: 78 observed, 74.35 expected, observed/expected ratio (o/e) 1.05, 90% interval 0.87 to 1.27. The upper end of that interval is the gene's LOEUF score, 1.27, which puts it in group 5 of 6, group 1 being the genes least tolerant of losing a copy. Missense variants: 787 observed, 786.7 expected, observed/expected ratio (o/e) 1, 90% interval 0.94 to 1.06. Synonymous variants: 323 observed, 317.35 expected, observed/expected ratio (o/e) 1.02, 90% interval 0.93 to 1.12.
Homologues: Orthologues: chimpanzee TOP1MT (99% identical), macaque TOP1MT (88% identical), pig TOP1MT (76% identical), mouse Top1mt (73% identical), guinea pig TOP1MT (72% identical), tropical clawed frog top1mt (70% identical), rat Top1mt (66% identical). Paralogues in human: TOP1 (66% identical).